BECN1 (beclin 1)
Diseases named in the same sentence as BECN1 in open-access papers (continued):
Sharing a sentence is not in itself a finding about the gene and the disease.
tumor (continued). "They upregulate tumour cell viability and autophagy and inhibit apoptosis through the LUCAT1/miR‐514a‐3p/ULK1 axis and PVT1/miR‐216b‐5p/Beclin 1 axis, respectively." (PMID 37837401, 2023). "Assessment of autophagy in primary tumor tissue is generally performed by determining indirect markers like LC3B, p62 or Beclin-1." (PMID 37686598, 2023). "Since P62 is a well-known receptor for autophagy, we also examined the expression of autophagy markers including ATG7, Beclin-1 and LC3B in xenograft tumor sections by IHC." (PMID 35216629, 2022). "In patients, for whom mass spectrometry protein data were publicly available from the Clinical Proteomic Tumor Analysis Consortium (CPTAC), BECN1 and ATG7 copy numbers also correlated with the respective protein level." (PMID 35681458, 2022). "Immunohistochemistry of 68 patients with CRC revealed a significant correlation between Beclin 1 levels and those of LC3 and 4E-BP1 and overexpression of LC3 in tumor tissues compared to normal tissues." (PMID 35912261, 2022). "Beclin 1 is a subunit of the PI3K-III complex and a tumor suppressor that plays an important function in autophagy and apoptosis." (PMID 36293239, 2022). "Expression level and release of the cytokine CCL5 were increased by inhibition of BECN1 via the MAPK8/JNK-JUN/c-Jun signaling pathway, resulting in tumor growth inhibition and massive natural killer cell infiltration into the tumor microenvironment." (PMID 35761331, 2022). "In general, there appear to be two main mechanisms in dopamine treatment for GBM: inhibiting tumor angiogenesis through the VEGF pathway and inducing cell autophagy mediated by the mTOR pathway or via the Beclin1 (BECN1)-dependent pathway." (PMID 36010960, 2022). "In the present study, miR-30a-3p directly targeted Beclin 1 and ATG5/12, which separately participate in the regulation of vesicle nucleation and elongation, leading to increased chemosensitivity and impaired tumor progression." (PMID 35449123, 2022). "The data indicate potential cardioprotective effects of preconditioning exercise on preserving cardiac structure and function, as well as regulating autophagic (beclin-1), inflammatory (TGF-β and MyD88), and atrophy (p-FOXO1) pathways during tumor bearing." (PMID 36531941, 2022). "BECN1 served as a negative regulator of CRC metastasis in Hu’s research, suggesting that BECN1 is a tumor suppressor." (PMID 35110535, 2022). "This protection contributed to preventing the increase of key genes and proteins of ubiquitin-proteasome and autophagy pathways in tumor-bearing mice, such as Atrogin-1, LC3B-II, Beclin-1 and p62." (PMID 35847939, 2022). "We conclude that single copies of the ATG7, BECN1, LC3, and ATG10 gene are largely sufficient to sustain autophagy and maintain tumor cell proliferation under treatment with 2DG and DCA." (PMID 35681458, 2022). "RT also protected skeletal muscle against tumor-induced elevated autophagy proteins LC3B-II, Beclin-1 and p62." (PMID 35847939, 2022). "Collectively, we concluded that blue LED irradiation exhibited anti‐tumour effects on OS by triggering ROS and EGFR/Beclin‐1‐mediated autophagy signalling pathway, representing a potential approach for human OS treatment." (PMID 33960631, 2021). "The positive expression frequencies of the autophagy-related proteins were demonstrated to be 84.00% (168/200) for Beclin 1, and 86.50% (173/200) for LC3 among the 200 CRC tumor samples." (PMID 33995628, 2021). "Previous reports showed that BECN1, an essential autophagy-related gene (ATG), was deleted in 40 to 75% of breast, ovarian, and prostate cancers, suggesting the role of autophagy in tumor growth suppression." (PMID 34895252, 2021). "The expression of the Beclin 1 (χ2 = 274.337, P < 0.001) and LC3 (χ2 = 281.999, P < 0.001) autophagy-related proteins was much higher in CRC tumor samples than in the intestinal mucosa group." (PMID 33995628, 2021).
tumor (continued). "The protein expression of mTOR and p62 were markedly downregulated, and the protein expression of ATG-7, Beclin-1, and LC3-II/LC3-I were markedly upregulated in the tumor tissues in the QYSL and RAPA groups compared with the model group." (PMID 34093717, 2021). "Thus, the overexpression of Beclin-1 could inhibit tumour development." (PMID 34575883, 2021). "ABA-induced autophagy was further revealed by increases in the expression levels of LC3-II and beclin 1 in ABA-treated, tumour-bearing mice detected by Western blotting." (PMID 32577848, 2021). "Previous data showed that shallow CNV of BECN1 and BRCA1 correlates with low level of mRNA in the tumor and with better prognosis of the patients." (PMID 33670664, 2021). "Difference in methylation levels of Beclin-1, bcl2, LC3 and ULK1 genes in tumor samples compared to normal tissues were analyzed." (PMID 33773561, 2021). "As expected, overall survival (p = 0.0088) and disease-free survival (p = 0.0575) were higher in the patients bearing a tumor with shallow deletion of both BECN1 and BRCA1 compared to those bearing a tumor with a diploid CNV of the two tumor suppressor genes." (PMID 33670664, 2021). "The IHC results showed that the protein level of Beclin-1 and LC3B increased, whereas the protein level of P62 decreased in the tumor tissues grown from HeLa cells, in the AL treatment groups compared with the control groups." (PMID 33927214, 2021). "Intermediate and strong staining scores of Beclin-1, LC-3, BNIP-3, and Parkin were significantly higher in tumor tissues compared to the adjacent matched control." (PMID 34490076, 2021). "Exercise also decreased proteolysis, which was confirmed by decreased autophagy (Beclin-1, LC3BI, and LC3BII gene expression, and p62 protein level) without an increase in protein synthesis (p-Akt, S6, p-AMPK) in C26 tumor-bearing and C26 oxfu mice." (PMID 34440525, 2021). "Intermediate and strong staining scores of MnSOD, Beclin-1, LC-3, BNIP-3, and Parkin were significantly higher in tumor tissues compared to the adjacent matched control." (PMID 34490076, 2021). "Studies show that Beclin-1 downregulation and HIF-1α overexpression are conducive to tumor progression and metastasis, and therefore portend poor prognosis." (PMID 34917504, 2021). "On the other hand, autophagy can be used as a tumor suppressor signal by selectively regulating key mediators such as p62, TWIST1, and beclin-1 to counteract the activation of EMT." (PMID 34887935, 2021). "Our study demonstrated that the anti‐tumour action induced by blue LED irradiation was mediated by both ROS and EGFR/Beclin‐1‐mediated autophagy signalling pathway in human OS." (PMID 33960631, 2021). "Beclin-1, LC-3, BNIP-3, and Parkin were highly scored as weak staining compared to tumor tissues (p < 0.05)." (PMID 34490076, 2021). "Therefore, beclin-1–mediated autophagy might be considered as a tumor angiogenesis factor for GC." (PMID 35153766, 2021). "Such a role was supported by studies showing that targeting BECN1, ATG5, and ATG7 promotes tumor initiation." (PMID 33718194, 2021). "To determine the prognostic role of BECN1 and BRCA1, we analyzed the survival of patients bearing a tumor with consistent CNV of the tumor suppressor genes, i.e., with both shallow deletion (240 cases) or diploid (50 cases) status." (PMID 33670664, 2021). "IHC and WB assay were also used to detect the expression level of beclin-1, LC3-II, and p62 to evaluate the effect of QFG on tumor cell autophagy progression." (PMID 34887935, 2021). "Staining for the biomarkers of autophagy (Beclin‐1, LC3‐II and P62) using immunofluorescence and immunohistochemistry showed that the tumour cells in the koPLAC8 group had higher autophagy activity compared with that in the control group." (PMID 32468683, 2020). "Vitamin K2 dose-dependently upregulated the expression of P62, Beclin-1 and LC3B II and activated Caspase-3 in tumor sections." (PMID 32382009, 2020).
tumor (continued). "Some of them involve the phosphorylation of Beclin 1 at different tyrosine residues that ultimately regulate the activity of the PI3KC3 and affect tumor growth." (PMID 33287140, 2020). "Prior research revealed that JNK1 phosphorylates BCL2 to disrupt the interaction of Beclin‐1 and BCL2, which induces autophagy activation in tumor cells." (PMID 32592208, 2020). "Taking this into consideration, Beclin 1-conjugated MNP were fabricated in order to promote the autophagy activity in cancer cells and further assist tumor growth regression capacity of PTT." (PMID 33212974, 2020). "The formation of VM structures correlated with tumor grade in GBM patients, as well as with the expression of Beclin-1, VEGF, and MMP2." (PMID 32707662, 2020). "We further evaluated the protein expressions of autophagy markers (ATG5, ATG7, Beclin-1, and LC3 B) and necroptosis markers (RIPK1, RIPK3) in NGP xenograft tumor tissues after rapamycin and MK-2206 combination treatment by Western Blot." (PMID 32116708, 2020). "Taken together, these data show that Beclin 1 tyrosine phosphorylation by oncogenic EGFR regulates autophagy and that it contributes to tumor progression." (PMID 31877888, 2019). "The activation of BECN1 is followed by direct phosphorylation of B-cell lymphoma 2 (BCL2), which in turn disrupts the interaction between BECN1 and BCL2 and induces autophagy in tumor cells." (PMID 31861079, 2019). "Autophagy-related markers, LC3, Beclin-1, and p62 expression was immunohistochemically assessed in HCC and adjacent non-tumor (ANT) tissues." (PMID 29961754, 2018). "Direct evidence showing the tumor suppressor function of autophagy comes from the fact that certain ATG-proteins, such as Beclin-1, exhibit an anti-oncogenic function." (PMID 28536348, 2017). "Immunohistochemistry showed low levels of miR-20a targets (BECN1, ATG16L1 and SQSTM1) in tumor tissues." (PMID 28628113, 2017). "Compared with miR-590-3p group or EMAP-II + TMZ group, miR-590-3p + EMAP-II + TMZ significantly up-regulated LC3-II and Beclin-1 protein expression and down-regulated p62/SQSTM1 protein expression in tumor tissues." (PMID 28348518, 2017). "We found that CD133-expressing stem-cells had significantly higher mRNA expression levels of BECN1, BNIP3L, MAPLC3B, CAIX and HIF1A than CD133-negative tumor cells (p < 0.05)." (PMID 28445132, 2017). "BECN1 and ATG14 genes were responsible for the vesicle nucleation stage, and were related with tumor progression." (PMID 30460069, 2017). "Compared with the control group, miR-590-3p, EMAP-II + TMZ or miR-590-3p + EMAP-II + TMZ significantly up-regulated LC3-II and Beclin-1 protein expression and down-regulated p62/SQSTM1 protein expression in tumor tissues." (PMID 28348518, 2017). "Numerous studies have shown that the expression levels of Beclin 1 are dysregulated in CRC tissues, especially in advanced stage tumor." (PMID 28938618, 2017). "Ursolic acid, a pentacyclic triterpenoid known for its anti-tumor effects, increased the expression of LC3-II, an autophagosome marker, and induced autophagy via the Beclin-1 and AKT/mTOR pathways." (PMID 29209152, 2017). "OVCAR3 is a cisplatin-resistant tumour cell genetically similar to TCGA assayed OV30, exhibiting monoallelic deletions of LC3 and BECN1, and forming appropriate high-grade histology in mice." (PMID 28198375, 2017). "However, recent studies suggest that loss of Beclin-1 may be a passenger mutation, since loss of BRCA1 and Beclin-1 itself does not have an effect on tumor suppressor functions." (PMID 28753959, 2017). "Direct evidence shows that the tumor suppressor function in autophagy comes from the fact that some ATG-proteins, such as Beclin-1, exhibit anti-oncogenic functions." (PMID 28930154, 2017). "Studies have shown that Beclin-1 is a tumor suppressor, and that the anti-apoptotic B-cell lymphoma 2 (Bcl-2) protein directly binds to the Bcl-2 homology 3 (BH3) domain of Beclin-1 to inhibit autophagy." (PMID 28753959, 2017).
tumor (continued). "Univariate Cox proportional hazard analysis showed that large tumor size, poor histological grade, positive LN metastasis, advanced GC, high TNM stage, high SIRT1, and Beclin-1 expression were significantly related to shorter OS and RFS (p < 0.05)." (PMID 28070138, 2016). "In multivariate analysis, tumor number, ASPP2, and BECN1 expression status remained the significant independent predictors of RFS and OS." (PMID 27929538, 2016). "A total of 59.8% (73/122) of the tumor samples in which ASPP2 had high expression, showed low expression of BECN1, whereas high expression of BECN1 was found in about 67.2% (43/64) of tumor samples in which ASPP2 was low expression." (PMID 27929538, 2016). "IHC staining was performed to determine the expression of Beclin 1, PTEN, and PDGFRβ in archived tumor samples from 18 of 33 patients who received treatment and were evaluable for response." (PMID 27213589, 2016). "For example, it has been reported that Beclin-1 is acetylated by p300 and deacetylated by SIRT1 at lysine residues 430 and 437 which further influences the autophagosome maturation and tumor growth." (PMID 28070138, 2016). "Beclin 1 and UVRAG function as tumor suppressor genes, and Beclin 1+/− mice were shown to be tumor-prone." (PMID 24956373, 2014). "On the other hand, granular-like positivity of BECLIN 1 and LC3, which is indicative of ongoing autophagy, was more frequently observed in tumours from patients with a better survival." (PMID 25136588, 2014). "Consistently, high level of expression of BECLIN 1 and LC3 in tumours is well correlated with the overall survival of the patients." (PMID 25136588, 2014). "The results showed that ISL with or without epirubicin significantly inhibited miR-25 expression in the tumor tissue; this was accompanied by increases in the expression of LC3-II, ULK1 and BECN1 as well as a decrease in the expression of ABCG2." (PMID 25026296, 2014). "To understand the role of LRPPRC in tumor development, previously we reported that LRPPRC forms a ternary complex with Beclin 1 and Bcl-2 to inhibit autophagy." (PMID 24722279, 2014). "Consistent with this view, Beclin-1, which is part of the class III PI3K complex that promotes autophagy, functions as a tumor suppressor in mammalian cells." (PMID 25328887, 2014). "A potential explanation for the Becn1 gene deletion effects in mice compared with the milder tumorigenic effects of Atg5 or Atg7 deletions might be that other functions of the BECN1 protein independent of its role in autophagy are causing the tumor phenotype." (PMID 25313680, 2014). "The autophagic genes beclin-1 and LC3 paly an important role in the development and progression of tumor." (PMID 23935917, 2013). "Another two autophagy markers, autophagy-related protein 7 (Atg7) and Atg6 (also known as Beclin-1), were also found to be decreased in PyVT(+/−)ADN(−/−) tumor cells." (PMID 24113220, 2013). "Notable overexpression of Beclin-1 protein and conversion of LC3-I to LC3-II were found in the SG511-BECN-treated tumor, confirming the role of autophagy in inhibiting tumor growth." (PMID 23765161, 2013). "Immunohistochemistry staining showed that Beclin 1 was lowly expressed in 67.9% (72/106) ICC and 73.0% (54/74) ECC specimen, especially in the tumor nest zone, whereas was moderately or strongly expressed in the normal adjacent tissues." (PMID 24303007, 2013). "The expression of Beclin-1 and LC3, which are widely used markers in mammalian autophagy, has been investigated in a variety of tumor types." (PMID 24282606, 2013). "The low levels of Beclin 1, Bcl-xL and Bad mRNA observed in HCC support their relationship in promoting tumorigenesis and favoring tumor cell progression." (PMID 22928777, 2012).
tumor (continued). "However, others have reported that autophagy may work as a tumor suppressor mechanism and promote cell death by working through Beclin-1, considered as a type II programmed cell death pathway, and prevent cancer cell proliferation through cell cycle arrest and therefore causing senescence." (PMID 23119048, 2012). "Notably, this study represents the first global exploration of BCc1 nanomedicine's potential to induce autophagy, a process mediated by autophagy-related genes (Beclin-1, ATG-4B, ATG-7, and mTOR), while evaluating tumor cell death." (PMID 41550506, 2026). "BCc1 treatment significantly increased Beclin-1 expression, comparable to cyclophosphamide-induced modulation, suggesting a nuanced mechanism that balances autophagy activation for tumor suppression without triggering cytoprotective resistance." (PMID 41550506, 2026). "Our data indicate an increased expression of the muscle-specific E3 ubiquitin ligase involved in the UPP, as well as elevated levels of the autophagy-initiating protein beclin-1 and the autophagosome marker protein LC3-II in the gastrocnemius muscles of C26 tumor-bearing mice." (PMID 40136406, 2025). "Similarly, treatment with the ferroptosis activator (Erastin) not only suppressed tumor volume but also decreased the expression of autophagy-related proteins (ATG5, ATG7, and BECN1), along with increased cell apoptosis." (PMID 41502518, 2025). "Our results demonstrated LC3B and Beclin-1 expression in the tumor vasculature, while p62 was not expressed." (PMID 39744218, 2025). "The H3K18la modification enhances transcription of rubicon-like autophagy enhancer (RUBCNL/Pacer), mediating the recruitment of the PtdIns3K complex through interaction with Beclin 1 (BECN1), thereby promoting the maturation of autophagosomes and enhancing tumor cell resistance to bevacizumab." (PMID 40589733, 2025). "Given the pronounced molecular heterogeneity of GBM, the functional output of beclin-1-dependent autophagy and its coupling to apoptosis is likely to differ across clinically relevant tumour states rather than representing a uniform programme." (PMID 41511337, 2025). "Interestingly, similar to BECN1 knockdown, ATG5 silencing also reversed the autophagy-promoting and tumor-suppressive effects of DHX9 silencing." (PMID 40659605, 2025). "And the tumor-suppressive effects of DHX9 silencing mediated by BECN1 is also not entirely autophagy-dependent." (PMID 40659605, 2025). "The combination of NDV, EVE, and Beclin-1 constitutes a multifaceted treatment approach designed to address tumor resistance and boost immune responses through increased ICD induction or improved tumor-infiltrating CD8 + T cells." (PMID 40403026, 2025). "This suggests that while ATG5, as one of the core components of the autophagy-initiating machinery, may be required for BECN1-mediated tumor-suppressive effects of DHX9 silencing, only BECN1 functions as the essential triggering factor." (PMID 40659605, 2025). "Targeting Becn1 to inhibit autophagy significantly restores the levels of serine protease GZMB/granzyme B within target cells under hypoxic conditions and induces tumor regression in vivo by promoting NK cell-mediated tumor cell killing." (PMID 41246345, 2025). "BECN1 had negative risk scores in two CRISPR screen datasets (Pan2018 OTI and PAN2018 Pmell), while OPTN had a negative risk score in M2 tumor-associated macrophages." (PMID 39859167, 2025). "Notably, Beclin-1 expression showed a positive correlation with hypoxia-inducible factor 1-alpha (HIF-1α), a hypoxia-inducible transcription factor known to promote tumour aggressiveness." (PMID 40805271, 2025).